INSIG1 (insulin induced gene 1)
Diseases named in the same sentence as INSIG1 in open-access papers (continued):
Sharing a sentence is not in itself a finding about the gene and the disease.
metabolic disorders (2 papers, 2021 to 2024). "miR-32 was shown to directly target INSIG1, which leads to the activation of SREBP and associated lipogenic gene programs, thereby promoting hepatic lipid accumulation and metabolic disorders." (PMID 39595599, 2024). "INSIG1 (cholesterol biosynthesis), which is known to be involved in the development of metabolic disorders upon treatment with clozapine, was differentially expressed in cells treated with clozapine." (PMID 35051043, 2021).
INSIG1 also shares sentences with these, for which no sentence is quoted: colorectal cancer (2 papers); type 2 diabetes (2); Alzheimer disease (1); amyotrophic lateral sclerosis (1); asthma (1); autism (1); Cardiovascular Disease (1); esophageal tumor (1); Hyperglycemia (1); hypertriglyceridemia (1); hyperuricemia (1); laryngeal carcinoma (1); liver disease (1); Nephropathy (1); neurodegenerative disease (1); osteogenesis imperfecta (1); ovarian carcinoma (1); polycystic ovary syndrome (1); triple-negative breast carcinoma (1); type I diabetes (1).